PAFAH1B2 (platelet activating factor acetylhydrolase 1b catalytic subunit 2)
Description:
Alpha2 catalytic subunit of the cytosolic type I platelet-activating factor (PAF) acetylhydrolase (PAF-AH (I)) heterotetrameric enzyme that catalyzes the hydrolyze of the acetyl group at the sn-2 position of PAF and its analogs and modulates the action of PAF. The activity and substrate specificity of PAF-AH (I) are affected by its subunit composition. The alpha2/alpha2 homodimer (PAFAH1B2/PAFAH1B2 homodimer) hydrolyzes PAF and 1-O-alkyl-2-acetyl-sn-glycero-3-phosphorylethanolamine (AAGPE) more efficiently than 1-O-alkyl-2-acetyl-sn-glycero-3-phosphoric acid (AAGPA). In contrast, the alpha1/alpha2 heterodimer(PAFAH1B3/PAFAH1B3 heterodimer) hydrolyzes AAGPA more efficiently than PAF, but has little hydrolytic activity towards AAGPE (By similarity). May play a role in male germ cell meiosis during the late pachytenestage and meiotic divisions as well as early spermiogenesis (By similarity).
Synonyms: HEL-S-303
Tractability: Antibody: its Gene Ontology location is reachable by antibodies, with high confidence. PROTAC: ubiquitination databases record sites on it; its protein half-life has been measured; a small molecule that binds it is known.
Target class: Enzyme; Hydrolase
Gene: Protein-coding gene on chromosome 11 (117,144,284 to 117,176,894, forward strand). Ensembl gene ENSG00000168092.
Subcellular location: Cytoplasm
Subcellular location (Human Protein Atlas): Cytosol; Nucleoli; Plasma membrane
Pathways (Reactome):
Immune System: Neutrophil degranulation
Vesicle-mediated transport: COPI-independent Golgi-to-ER retrograde traffic
Gene Ontology:
Molecular function: protein binding; 1-alkyl-2-acetylglycerophosphocholine esterase activity; platelet-activating factor acetyltransferase activity; protein heterodimerization activity; protein homodimerization activity; identical protein binding; protein-containing complex binding
Biological process: positive regulation of macroautophagy; lipid metabolic process; platelet activating factor catabolic process; spermatogenesis
Cellular component: 1-alkyl-2-acetylglycerophosphocholine esterase complex; cytosol; extracellular exosome; cytoplasm; extracellular region; ficolin-1-rich granule lumen; secretory granule lumen
Genetic constraint (gnomAD): Loss-of-function variants: 5 observed, 15.66 expected, observed/expected ratio (o/e) 0.32, 90% interval 0.17 to 0.67. The upper end of that interval is the gene's LOEUF score, 0.67, which puts it in group 2 of 6, group 1 being the genes least tolerant of losing a copy. Missense variants: 144 observed, 211.43 expected, observed/expected ratio (o/e) 0.68, 90% interval 0.59 to 0.78. Synonymous variants: 78 observed, 79.17 expected, observed/expected ratio (o/e) 0.99, 90% interval 0.82 to 1.19.
Cancer hallmarks: change of cellular energetics (promotes)
Homologues: Orthologues: chimpanzee PAFAH1B2 (100% identical), macaque PAFAH1B2 (100% identical), pig PAFAH1B2 (100% identical), rabbit PAFAH1B2 (100% identical), dog PAFAH1B2 (99% identical), mouse Pafah1b2 (99% identical), rat Pafah1b2 (99% identical), guinea pig Pafah1b2 (88% identical), tropical clawed frog pafah1b2 (83% identical), zebrafish pafah1b2 (69% identical), Drosophila melanogaster Paf-AHalpha (46% identical). Paralogues in human: PAFAH1B3 (62% identical), ICE1 (24% identical).
Diseases named in the same sentence as PAFAH1B2 in open-access papers:
PAFAH1B2 is named in the same sentence as 25 diseases in open-access papers, as found by Europe PMC text mining. Sharing a sentence is not in itself a finding about the gene and the disease. The quoted sentences say what the papers report.
breast carcinoma (3 papers, 2021 to 2022). "Blocking PAFAH1B3 and PAFAH1B2 have been shown to extensively affect lipid metabolism and upregulate the expression of lipids that inhibit breast cancer growth." (PMID 34490100, 2021). "Blockade of PAFAH1B2 and PAFAH1B3 causes a heightened level of tumor-suppressing lipids and damages cancer pathogenicity in breast cancer and several other types of cancer." (PMID 33494814, 2021). "In line with our findings, PAFAH1B2 was no significantly upregulated in human breast tumors, but targeting PAFAH1B2 could also significantly impaired proliferation, survival, migration, and invasiveness in breast cancer cells." (PMID 34490100, 2021). "GDF11, CD151, PAFAH1B2 and YTHDF2 may play a pivotal role in the predisposition of metastasis to the bone from breast cancer, whilst DPP9, FAS, ZNF519, RPP14 and FAU may be actively involved in the adaptative colonisation of metastatic breast cancer cells in bone." (PMID 35685372, 2022). "The overall survival rates of breast cancer patients based on the expression of these three genes (SMS, PAFAH1B2 and PDK3) were analyzed by UCSC Xena (data retrieved on November 24, 2020)." (PMID 33494814, 2021). "However, the specific biological functions of SMS, PAFAH1B2, or PDK3 need to be further investigated in breast cancer." (PMID 33494814, 2021).
B-cell lymphomas (1 paper, 2020). "PAFAH1B2, which is involved in ether lipid metabolism, may also be broadly dysregulated in many types of cancer and its over-expression at the transcriptional and at the protein levels in MYC-negative high-grade B-cell lymphomas is associated with good prognosis." (PMID 32373530, 2020).
coagulopathy (1 paper, 2016). "While the decreasing of PAFAH1B2 in H7N9 infection maybe another reason of infection-induced vascular permeability and coagulopathy in our study." (PMID 27223893, 2016).
coronary artery disease (1 paper, 2019). "Because triglyceride level is a causal factor for cardiovascular disease, we explored Gene2Pheno results for PAFAH1B2 in the additive analysis of coronary artery disease in CARDIoGRAM C4D." (PMID 30624610, 2019).
COVID-19 (1 paper, 2023). A disease caused by infection with severe acute respiratory syndrome coronavirus 2. "We showed a significant increase in the gene expression of PAFAH1B1 in the COVID-19 GCs group, but there was no change in the expression of PAFAH1B2 and PAFAH1B3." (PMID 36851787, 2023).
diabetes (1 paper, 2022). "Thus, based on our manual inspection of the metabolomics-proteomics data and in line with the evidence, we suggest that simulated diabetes evokes inflammation on BCAEC and that PAFAH1B2 and LYPLA1 play a role in modulating such process." (PMID 35835939, 2022).
glioma (1 paper, 2020). A benign or malignant brain and spinal cord tumor that arises from glial cells (astrocytes, oligodendrocytes, ependymal cells). "Collectively, our experiments indicate that the MAFP-resistant TAMRA-FP signal in the tumor is principally due to neutrophil serine proteases migrating in the ~ 25 kDa band, while the bulk of MAFP-sensitive activity in glioma is likely due to PAFAH1b3 and PAFAH1b2." (PMID 32190011, 2020). "Future work should elucidate the role of PAFAH1b3 and PAFAH1b2 in glioma." (PMID 32190011, 2020).
Hypertension (1 paper, 2021). The presence of chronic increased pressure in the systemic arterial system. "Hence, overexpression of miR-212-5p and PAFAH1B2 may serve as a potential therapeutic strategy for hypertension." (PMID 33760887, 2021). "In contrast, our study suggests that PAFAH1B2 plays a role in inhibiting VSMC proliferation and contraction in hypertension." (PMID 33760887, 2021).
hypopharyngeal squamous cell carcinoma (1 paper, 2023). "PAFAH1B2 as one of the catalytic subunits of type I PAF-AH (Platelet-activating factor acetylhydrolase) was associated with poor prognosis and affected proliferation in hypopharyngeal squamous cell carcinoma." (PMID 37897503, 2023).
leukemia (1 paper, 2020). A malignant (clonal) hematologic disorder, involving hematopoietic stem cells and characterized by the presence of primitive or atypical myeloid or lymphoid cells in the bone marrow and the blood. "Interestingly, we found different expression trends for PAFAH1B2 between the childhood and adult leukemia metabolic profiles." (PMID 32373530, 2020).
male infertility (1 paper, 2014). The inability of the male to effect fertilization of an ovum after a specified period of unprotected intercourse. "Recently, a new testis-specific protein isoform of Pafah1b2 with possible role in spermatogenesis has been identified, the knock-out of which causes male infertility in the mouse." (PMID 24712907, 2014).
ovarian carcinoma (1 paper, 2021). A malignant neoplasm originating from the surface ovarian epithelium. "According to these results, PAFAH1B2 may play an important regulatory role in in ovarian cancer cells abnormal cell proliferation and adhesion." (PMID 34930255, 2021).
pancreatic ductal adenocarcinoma (1 paper, 2021). An infiltrating adenocarcinoma that arises from the epithelial cells of the pancreas. "PAFAH1B2 also regulates the process of EMT in pancreatic ductal adenocarcinoma." (PMID 33760887, 2021).
prostate carcinoma (1 paper, 2023). A carcinoma that arises from epithelial cells of the prostate gland. "Nonetheless, PAFAH1B2 expression has been reported as a prognostic marker for MM in validation analysis while PTPN4 has been found to serve as an upstream therapeutic target in the treatment of prostate cancer, indicating the potential for the two proteins as future research entry points." (PMID 37775746, 2023).
T cell lymphomas (1 paper, 2019).
cancer (10 papers, 2014 to 2025). A tumor composed of atypical neoplastic, often pleomorphic cells that invade other tissues. "Some studies have shown that PAFAH1B2 plays a role in promoting cancer, and studies are underway for the development of drugs that inhibit PAFAH1B2." (PMID 33760887, 2021). "PAFAH1B2 enhances aggressiveness and MYCL regulates hallmarks of cancer including proliferation and immune evasion." (PMID 37897503, 2023). "Screening 107 overall survival-related cancer genes and 402 interacting gene pairs, 6 genes: CRLF2, HSP90AA1, MAP2K1, PAFAH1B2, MYCL and SET genes, were identified and a transcriptional score was obtained." (PMID 37897503, 2023). "PAFAH1B2 is the catalytic subunit of PAF-AH and has been reported to be overexpressed in several cancers." (PMID 33760887, 2021). "Pharmacological blockade of PAFAH1B2 and PAFAH1B3 impaired cancer pathogenicity across a number of different types of cancer cells, including prostate cancer." (PMID 30197761, 2018). "Therefore, we used ONCOMINE online cancer database to analyze the mRNA expression of PAFAH1B1 and PAFAH1B2 in HCC and found that the mRNA expression of PAFAH1B1 and PAFAH1B2 was no significant changes in HCC." (PMID 34490100, 2021).
tumor (6 papers, 2016 to 2025). "Bioinformatic analysis revealed miR-3613-3p might regulate cell cycle signaling pathway by targeting SMS, PAFAH1B2, or PDK3 to restrain tumor progression." (PMID 33494814, 2021). "Additionally, miR-3613-3p might regulate cell cycle by targeting SMS, PAFAH1B2, or PDK3 to restrain tumor progression." (PMID 33494814, 2021).
adenocarcinoma of the (1 paper, 2017). "The GPR137 gene has also been identified in two fusions: with PAFAH1B2 and USP32 in adenocarcinoma of the lung and of the breast, respectively." (PMID 28186972, 2017).
infection (1 paper, 2016). The state of being infected such as from the introduction of a foreign agent such as serum, vaccine, antigenic substance or organism. "The results further prove that the H7N9 virus seriously affect the synthesis of PAFAH1B2 in A549 cells in the later phase of infection." (PMID 27223893, 2016). "In 3 independent western blot analyses (P<0.05), as shown in, compared with the H1N1pdm09 infection, the down- or up-regulated proteins of CAPZA1 (33KDa), OAT (49KDa), PCBP1 (37KDa), EIF5A (18KDa), PAFAH1B2 (26KDa) in H7N9 infection were consistent with the 2-D DIGE results." (PMID 27223893, 2016).
PAFAH1B2 also shares sentences with these, for which no sentence is quoted: avian influenza (1 paper); bone metastasis (1); breast tumors (1); cardiovascular disease (1); herpesvirus infections (1); viral infections (1).